CAP1 (cyclase associated actin cytoskeleton regulatory protein 1)
Description:
Directly regulates filament dynamics and has been implicated in a number of complex developmental and morphological processes, including mRNA localization and the establishment of cell polarity.
Synonyms: CAP; CAP1-PEN
Tractability: Antibody: its Gene Ontology location is reachable by antibodies, with high confidence; UniProt places it where antibodies can reach, with medium confidence. PROTAC: UniProt records ubiquitination sites on it; ubiquitination databases record sites on it; its protein half-life has been measured.
Gene: Protein-coding gene on chromosome 1 (40,039,735 to 40,072,767, forward strand). Ensembl gene ENSG00000131236.
Subcellular location: Cell membrane
Subcellular location (Human Protein Atlas): Cytosol
Pathways (Reactome):
Developmental Biology: Role of ABL in ROBO-SLIT signaling
Hemostasis: Platelet degranulation
Immune System: Neutrophil degranulation
Gene Ontology:
Molecular function: protein binding; adenylate cyclase binding; actin binding
Biological process: actin filament organization; activation of adenylate cyclase activity; cell morphogenesis; establishment or maintenance of cell polarity; signal transduction; cytoskeleton organization; modification of postsynaptic actin cytoskeleton
Cellular component: extracellular exosome; focal adhesion; azurophil granule lumen; cytoplasm; extracellular region; cortical actin cytoskeleton; glutamatergic synapse; plasma membrane; postsynapse; presynapse
Genetic constraint (gnomAD): Loss-of-function variants: 8 observed, 40 expected, observed/expected ratio (o/e) 0.2, 90% interval 0.12 to 0.36. The upper end of that interval is the gene's LOEUF score, 0.36, which puts it in group 1 of 6, group 1 being the genes least tolerant of losing a copy. Missense variants: 316 observed, 441.93 expected, observed/expected ratio (o/e) 0.72, 90% interval 0.65 to 0.79. Synonymous variants: 145 observed, 159.58 expected, observed/expected ratio (o/e) 0.91, 90% interval 0.79 to 1.04.
Homologues: Orthologues: chimpanzee CAP1 (99% identical), macaque CAP1 (98% identical), rat Cap1 (94% identical), mouse Cap1 (94% identical), pig CAP1 (93% identical), guinea pig Cap1 (92% identical), tropical clawed frog cap1 (70% identical), zebrafish cap1 (64% identical), Drosophila melanogaster capt (47% identical), Caenorhabditis elegans cas-1 (42% identical), Caenorhabditis elegans cas-2 (33% identical). Paralogues in human: CAP2 (63% identical).
Diseases named in the same sentence as CAP1 in open-access papers:
CAP1 is named in the same sentence as 82 diseases in open-access papers, as found by Europe PMC text mining. Sharing a sentence is not in itself a finding about the gene and the disease. The quoted sentences say what the papers report.
breast carcinoma (22 papers, 2015 to 2022). "For example, it has been shown that CAP1 expression was associated with the histological grade and Ki-67 expression in breast cancer, and that a high serum level of CAP1 in patients with NSCLC was associated with low tumor differentiation." (PMID 37226274, 2022). "CAP1 was recently reported upregulated within a breast cancer risk-associated multi-gene classifying signature enriched in high adipose content breast tissue." (PMID 33738261, 2021). "Further mechanistic studies are required to investigate CAP1-associated pathways in obesity-related breast cancer." (PMID 33738261, 2021). "Previous breast cancer studies have shown high CAP1 gene expression to be associated with poor tumor characteristics and impaired relapse-free and overall survival." (PMID 32560703, 2020). "Low CAP1 tumor expression was associated with higher body fatness and worse survival outcomes in breast cancer patients." (PMID 33072768, 2020). "Low CAP1 tumor expression was associated with higher body fatness and worse survival outcomes in breast cancer patients with effect modification by adiposity and ER status." (PMID 32560703, 2020). "In summary, our results demonstrate that lower CAP1 protein expression in early breast cancer was linked to higher adiposity status, more aggressive disease characteristics, and reduced long-term survival in women with breast cancer." (PMID 32560703, 2020). "The loss of CAP1 expression affects the breast cancer cell cycle, retards the glioma cells proliferation and inhibits cell cycle progression in epithelial ovarian cancer cells." (PMID 33072768, 2020). "CAP1 is expressed across a large panel of breast cancer cell lines and primary human tumor and high CAP1 expression is associated with poor tumor characteristics and impaired prognosis among breast cancer patients." (PMID 33072768, 2020). "In a study, CAP1 gene and Resistin gene variants were associated with increased risk of breast cancer among Mexican women." (PMID 33072768, 2020). "Altered ERK activities at least partially underlie the cell context-dependent roles of CAP1 in the proliferation of breast cancer cells, while likely also contribute to the phenotypes in cancer cell invasiveness." (PMID 31151140, 2019). "Knockdown of CAP1 in breast cancer cells caused distinct alterations in FAK in the metastatic and non-metastatic breast cancer cells." (PMID 30894654, 2019). "It was recently reported that certain resistin (RETN) and CAP1 gene variants were associated with increased risk of breast cancer among Mexican women." (PMID 30524378, 2018). "The recent discovery of the novel resistin receptor CAP1 will facilitate further exploration of the resistin-CAP1 link in obesity-associated breast cancer." (PMID 30524378, 2018). "Stratification according to tumor ER status showed that the associations between high CAP1 and breast cancer outcomes were most pronounced among ER-positive tumors (Log rank; P ≤ 0.038)." (PMID 30524378, 2018). "This indirect mechanism is noticeably distinct from the direct effect of resistin on breast cancer cells, such as the enhanced tumor growth and metastatic ability of breast cancer cells via toll-like receptor 4 (TLR4) or adenylyl cyclase-associated protein 1 (CAP1)-mediated pathways." (PMID 36104403, 2022). "The adipokine receptor adenylyl cyclase-associated protein-1 (CAP1) has been implicated in the progression of breast cancer, but results are conflicting and the underlying molecular mechanisms are still unknown." (PMID 33738261, 2021). "We profiled phosphorylation patterns and identified several potential pathways whereby obesity-associated adipocyte secretome and CAP1 may affect cell proliferation and migration in breast cancer." (PMID 33738261, 2021).
breast carcinoma (continued). "While high CAP1 gene expression has been linked to poor tumor characteristics and worse breast cancer prognosis, associations between CAP1 protein expression and body constitution and clinical outcome in breast cancer are is yet unknown." (PMID 32560703, 2020). "The aim of this study was to evaluate whether CAP1 tumor expression was associated to body constitution and clinical outcome in breast cancer." (PMID 32560703, 2020). "Based on previous cellular and gene expression studies, our hypotheses were that an obese body composition would be associated with high CAP1 expression in tumors and that breast cancer patients with high CAP1 tumor expression would have worse prognosis." (PMID 32560703, 2020). "The TNF-α c.-308G>A (rs1800629) polymorphism was found to be associated with breast cancer risk in a study conducted in Mexico, and another Mexican study found associations between the RETN c.-225C>G (rs1862513) and CAP1 c.881G>A (rs35749351) polymorphisms and breast cancer risk." (PMID 30781715, 2019). "Considering the independent prognostic role of CAP1 shown in the present study and the importance of CAP1-related biological processes in breast cancer, further investigations are needed to elucidate the clinical implication of the resistin-CAP1 link in obesity-associated breast cancer." (PMID 30524378, 2018). "In addition, high CAP1 expression was associated with poor breast cancer outcomes in all subtypes." (PMID 34944905, 2021). "Therefore, a potential conservation of this interaction in breast cancer cells may explain that the depletion of CAP1 causes the activation of Abl, and consequently that of ERK." (PMID 31151140, 2019). "In this study, molecular and cellular effects in breast cancer cells by stimulation of adipocytes under normal or obese-like conditions, and potential involvement of CAP1, were assessed." (PMID 33738261, 2021). "Resistin mediates breast cancer epithelial-mesenchymal transition through adenylate cyclase-related protein 1 (CAP1), thereby promoting breast cancer cell metastasis." (PMID 34485124, 2021). "Assessment of CAP1 knockdown in the breast cancer cells was evaluated over 3, 5, and 7 days post transfection, the time period required for the subsequent experiments." (PMID 33738261, 2021). "The breast cancer cell proliferation was enhanced in response to adipocyte secretome stimulation, and knockdown of CAP1 in both ER-positive T47D and ER-negative MDA-MB-231 cells decreased proliferation, compared with CAP1 expressing cells." (PMID 33738261, 2021). "Similar effects by CAP1 knockdown on ERK1/2 phosphorylation have been demonstrated in the breast cancer cell lines BT-549 and MDA-MB-231 previously, however this resulted in increased proliferation which is in contrast to our results." (PMID 33738261, 2021). "In conclusion, we designed a culture system to study the effects of adipocyte secretome on CAP1 expressing and CAP1 silenced breast cancer cells." (PMID 33738261, 2021). "This is the first study to demonstrate involvement of CAP1 in adipocyte-mediated breast cancer cell proliferation." (PMID 33738261, 2021). "CAP1 silencing has previously been shown to impact breast cancer cell proliferation and migration in a context dependent manner." (PMID 33738261, 2021). "Second, patients with low tumor expression of CAP1 had an adverse breast cancer-specific and overall clinical outcome, with evidence of a stronger effect in lean patients." (PMID 32560703, 2020). "Additional large-scale studies are needed to fully elucidate the prognostic role of CAP1 in breast cancer and further investigate its clinical impact on breast cancer progression and disease recurrence." (PMID 32560703, 2020). "In order to test this, we assessed tumor-specific CAP1 protein expression and anthropometric measures in a cohort of 1016 patients with incident breast cancer and long-term follow-up within the prospective population-based Malmö Diet and Cancer Study (MDCS)." (PMID 32560703, 2020).
breast carcinoma (continued). "Under obese conditions, the adipocyte secretome has been shown to stimulate membrane protrusions and motility in CAP1-expressing breast cancer cells." (PMID 32560703, 2020). "Patients with low to moderate CAP1-expressing tumors were older at breast cancer diagnosis (P < 0.001) compared to patients with tumors of high CAP1 expressions." (PMID 32560703, 2020). "In this prospective cohort study, the clinical impact of CAP1 tumor expression was evaluated in relation to body constitution and long-term survival outcomes in breast cancer." (PMID 32560703, 2020). "Here, the objective was to investigate the interplay between body composition and CAP1 tumor expression regarding breast cancer outcome through long-term survival analyses." (PMID 32560703, 2020). "Two earlier breast cancer studies have assessed tumor CAP1 protein expression via IHC and report CAP1 positivity to be associated with unfavorable tumor characteristics (histologic grade III, ER-negative, lymph node positive)." (PMID 32560703, 2020). "Taken together, these results support that FAK is responsible, at least partially, for mediating CAP1 signals to regulate ERK in the metastatic breast cancer cells." (PMID 31151140, 2019). "Our findings that the FAK/ERK axis mediates CAP1 signals represent an important contribution to the knowledge on how CAP1 controls both invasiveness and proliferation in breast cancer cells." (PMID 31151140, 2019). "Few Latin American studies tested the association between genes in inflammation and energy balance pathways and breast cancer risk (TNF-α, RETN, CAP1, and PTGS2 genes)." (PMID 30781715, 2019). "In summary, we found that CAP1 not only controls breast cancer cell invasiveness, which was more of an anticipated one, but it also regulates cancer cell proliferation." (PMID 31151140, 2019). "We unraveled cell context-dependent roles for CAP1 in regulating the invasiveness of breast cancer cells, as well as a role in controlling the proliferation of cancer cells." (PMID 31151140, 2019). "Our studies unravel profound and complex roles for CAP1, involving key functions including adhesion, invasiveness, and proliferation in breast cancer cells." (PMID 31151140, 2019). "We also detected increased anchorage-independent growth in the CAP1-knockdown metastatic breast cancer cells." (PMID 31151140, 2019). "These mechanistic insights will surely help us better to understand the somewhat unexpected context-dependent roles for CAP1 in the invasiveness and proliferation of breast cancer cells." (PMID 31151140, 2019). "In HeLa and metastatic breast cancer cells, depletion of CAP1 leads to activation of FAK and enhanced cell adhesion, while in non-metastatic breast cancer cells it actually reduced FAK activity and cell adhesion." (PMID 30894654, 2019). "It is therefore possible that FAK, which is indeed activated in the CAP1-knockdown metastatic breast cancer cells, was actually responsible for ERK activation." (PMID 31151140, 2019). "We will next discuss the role of the FAK/ERK axis, and possibly Rap1, in mediating CAP1 signals to control breast cancer cell adhesion, invasiveness, and proliferation, largely based on our latest findings." (PMID 31151140, 2019). "It has been reported that knockdown of CAP1 in some mammalian cell types, including HeLa and metastatic breast cancer cells, led to significantly increased cell size, a phenotype we previously confirmed to be specific to knockdown of CAP112,18." (PMID 30894654, 2019). "In HeLa and metastatic breast cancer cells, knockdown of CAP1 led to activation of FAK, and consistently, enhanced cell spreading and adhesion." (PMID 30894654, 2019). "We recently identified a novel role for CAP1 in regulating the proliferation of breast cancer cells, where depletion of CAP1 exerts cell context-dependent effects on proliferation, accompanied with consistent alterations in ERK activity." (PMID 30894654, 2019).
breast carcinoma (continued). "Along with findings from other studies that also support the involvement of CAP1 in breast cancer cell functions, they carry important implications in targeted therapeutics for the disease." (PMID 31151140, 2019). "In breast cancer, CAP1 has been suggested to negatively regulate E-cadherin expression, thus reducing cell adhesion and promote migration." (PMID 30524378, 2018). "The prognostic significance of CAP1, categorized into tertiles based on the CAP1 log2 gene expression levels, and breast cancer outcomes were evaluated." (PMID 30524378, 2018). "Similar to the expression in cell lines, CAP1 was expressed across breast cancer subtypes, with higher expression found among ER− relative to ER+ tumors (P = 0.025), as well among tumor grades 2 and 3 relative to grade 1 (P = 0.016)." (PMID 30524378, 2018). "The conflicting literature reports highlight the importance of further studies to map the role of CAP1 in breast cancer progression." (PMID 30524378, 2018). "The newly identified resistin receptor, CAP1, was expressed across a large panel of breast cancer cell lines and primary breast tumors." (PMID 30524378, 2018). "Herein, we show for the first time that CAP1 is expressed across a large panel of breast cancer cell lines and primary human tumors." (PMID 30524378, 2018). "Given the recent discovery that resistin binds and acts through the CAP1 receptor, the relative CAP1 gene expression levels were further explored across a panel of 47 breast cancer cell lines." (PMID 30524378, 2018). "Altogether, these data demonstrate the differential expression of CAP1 across breast cancer subtypes and imply the role of CAP1 in both proliferative and cell motility processes." (PMID 30524378, 2018). "Yet, high CAP1 expression among breast cancer patients with ER+ or lymph node positive tumors was associated with significantly shorter overall and relapse-free survival, compared with low or intermediate expression." (PMID 30524378, 2018). "Stratification according to breast cancer clinical subtypes showed that the CAP1 mRNA expression (Log2) was highest in the basal B subgroup with more mesenchymal-like cell lines, followed by the basal A and lowest among the luminal-like cell lines (P = 0.007)." (PMID 30524378, 2018). "In the Oncomine analysis, CAP1 was found to be unregulated in various cancer types, but deregulated in leukemia and breast cancer." (PMID 28423713, 2017). "Overexpression of a resistin receptor, adenylyl cyclase-associated protein 1 (CAP1), was also reported in epithelial ovarian cancer and breast cancer, which are also known as obesity-related malignant tumors." (PMID 28422056, 2017). "These mechanistic insights carry important implications in ultimately developing strategies targeting CAP1 in the treatment of breast cancer, which is a highly diverse disease." (PMID 27173014, 2016). "Further efforts will be directed toward dissecting potential roles played by FAK and Abl in leading to the altered ERK activities in the CAP1 knockdown breast cancer cells." (PMID 27173014, 2016). "We report here our findings of cell context-dependent functions for CAP1 in the metastatic potential in breast cancer cells." (PMID 27173014, 2016). "Here we report our findings that CAP1 exerts cell type-dependent functions in the invasiveness of breast cancer cells." (PMID 27173014, 2016). "Our studies delineate a pivotal role for the ERK-GSK3/Snail/E-cadherin axis in mediating both CAP1 functions in breast cancer cells." (PMID 27173014, 2016). "Taken together, our results support that CAP1 also functions in breast cancer cell proliferation, again mediated by ERK-centered cell signaling." (PMID 27173014, 2016). "Given the contradictory evidence available on up-regulation of CAP1 in human cancers including breast cancer, we examined and compared CAP1 expression in a panel of breast cancer cells." (PMID 27173014, 2016).